MYADM (myeloid associated differentiation marker)
Synonyms: SB135
Tractability: Antibody: its Gene Ontology location is reachable by antibodies, with high confidence; UniProt predicts a signal peptide or a membrane-spanning region. PROTAC: its protein half-life has been measured.
Gene: Protein-coding gene on chromosome 19 (53,864,763 to 53,878,125, forward strand). Ensembl gene ENSG00000179820.
Subcellular location: Membrane
Subcellular location (Human Protein Atlas): Nuclear speckles
Gene Ontology:
Molecular function: protein binding
Biological process: cell-cell junction maintenance; establishment of endothelial barrier; intracellular signal transduction; membrane raft organization; negative regulation of actin filament polymerization; negative regulation of gene expression; negative regulation of heterotypic cell-cell adhesion; positive regulation of cell migration; positive regulation of substrate adhesion-dependent cell spreading; protein localization to plasma membrane raft; regulation of cell-substrate adhesion
Cellular component: cell-cell junction; cortical actin cytoskeleton; membrane raft; plasma membrane; ruffle; membrane
Genetic constraint (gnomAD): Loss-of-function variants: 0 observed, 3.08 expected, observed/expected ratio (o/e) 0, 90% interval 0 to 0.96. That is too few expected variants to judge how well the gene tolerates losing a copy. Missense variants: 416 observed, 456.68 expected, observed/expected ratio (o/e) 0.91, 90% interval 0.84 to 0.99. Synonymous variants: 224 observed, 217.36 expected, observed/expected ratio (o/e) 1.03, 90% interval 0.92 to 1.15.
Homologues: Orthologues: chimpanzee MYADM (99% identical), macaque MYADM (98% identical), dog MYADM (92% identical), rabbit MYADM (89% identical), rat Myadm (84% identical), guinea pig MYADM (84% identical), mouse Myadm (84% identical), tropical clawed frog myadm (52% identical), zebrafish myadma (51% identical), zebrafish myadmb (45% identical). Paralogues in human: MYADML2 (38% identical).
Diseases named in the same sentence as MYADM in open-access papers:
MYADM is named in the same sentence as 44 diseases in open-access papers, as found by Europe PMC text mining. Sharing a sentence is not in itself a finding about the gene and the disease. The quoted sentences say what the papers report.
Hypertension (4 papers, 2019 to 2023). The presence of chronic increased pressure in the systemic arterial system. "MYADM has been implicated in atherosclerotic disease and hypertension as a target of miR-182, which was previously found to modulate human smooth muscle cell differentiation, proliferation, and migration." (PMID 37345137, 2023). "Previous studies reported that the expression of MYADM (myeloid associated differentiation marker) induced hypertension, but this gene might be liable for advancement of T1D in patients with hypertension." (PMID 33827531, 2021). "A number of transcriptome-wide meta-analyses aimed at identifying genes involved in hypertension detected MYADM as a candidate." (PMID 37345137, 2023).
asthma (2 papers, 2021 to 2023). "The goal of this study was to determine if MYADM expression patterns were altered in asthma and/or rhinovirus infection and if increased MYADM expression is associated with increased asthma-associated factors." (PMID 37638015, 2023). "We also discovered that among asthmatic patients, MYADM expression is markedly increased in human airway epithelial cells and MYADM levels are associated with more severe asthma." (PMID 37638015, 2023). "In our attempt to learn more about MYADM and its connection to severe asthma, we chose to examine the response to Rhinovirus a virus known to be associated with asthma exacerbations." (PMID 37638015, 2023). "While we are unable to test this in our current work, future studies should determine if SP-A levels in asthma patients are negatively associated with MYADM levels." (PMID 34862427, 2021). "While we find that SP-A needs MYADM expression on eosinophils in order to properly induce apoptosis, the SARP data suggests increased epithelial MYADM expression is associated with more eosinophils and worse asthma phenotypes." (PMID 34862427, 2021). "Data analysis revealed that airway epithelial cell (AEC) mRNA expression of MYADM was significantly associated with asthma severity and asthma related phenotypes." (PMID 34862427, 2021). "MYADM epithelial expression has been shown to associate with asthma severity." (PMID 37638015, 2023). "In addition, several parameters associated with type 2 high asthma were also significantly associated with MYADM AEC gene expression." (PMID 34862427, 2021). "However, we were able to assess the association of MYADM airway epithelial cell (AEC) mRNA expression with asthma status, along with other parameters of asthma, in a subgroup of the Severe Asthma Research Program (SARP) III cohort." (PMID 34862427, 2021). "Additionally, we show that epithelial expression of MYADM is associated with asthma severity- which warrants further study." (PMID 34862427, 2021). "Additionally, MYADM expression was strongly associated with increases in inflammatory genes, which may contribute to more severe asthma and RV-linked asthma exacerbations." (PMID 37638015, 2023). "Taken together, our studies provide the first evidence of MYADM as a novel SP-A-associated protein that is necessary for SP-A to induce eosinophil apoptosis and we bring to light the potential importance of this previously unrecognized transmembrane protein in patients with asthma." (PMID 34862427, 2021). "Taken together, our studies show that MYADM is a novel association partner for SP-A on eosinophils that is necessary for SP-A to induce eosinophil apoptosis and we bring to light the potential importance of this previously unrecognized transmembrane receptor in patients with asthma." (PMID 34862427, 2021). "Our studies show that in a mouse model of asthma and during RV-1B infection of primary human AECs, increased MYADM expression is observed." (PMID 37638015, 2023). "Further studies are warranted to better determine how MYADM expression is upregulated in the context of asthma and RV infection." (PMID 37638015, 2023). "In the mouse model of asthma, MYADM expression was predominantly on the luminal side of airway epithelial cells." (PMID 37638015, 2023). "We had recently found that blocking of MYADM in a murine asthma model disrupts eosinophil clearance, leads to increased airway hyperresponsiveness, and results in increased mucus metaplasia in the airways." (PMID 37638015, 2023). "Our group recently reported that blocking the activity of MYADM in a murine asthma model disrupts eosinophils clearance, increases airway hyperresponsiveness, and results in increased mucus production." (PMID 37638015, 2023). "Further studies are needed to better define mechanisms by which epithelial-expressed MYADM participates in asthma phenotypes." (PMID 34862427, 2021).
asthma (continued). "Studies were also conducted using the less eosinophilic, but more relevant environmental allergen, HDM model to assess the importance of the SP-A:MYADM interaction to asthma in vivo." (PMID 34862427, 2021). "Most interestingly, in regards to our findings in mouse models and ex vivo eosinophil studies, increased eosinophil counts in the blood significantly correlated with increased MYADM AEC gene expression (p = 0.0044) in asthma patients." (PMID 34862427, 2021). "Taken together, our data provide evidence that suggests that MYADM may contribute to the pathogenesis of asthma by mediating inflammatory responses in the lung." (PMID 37638015, 2023). "With MYADM expression increased in asthma and during acute RV infection, enhanced MYADM activity could therefore contribute to more pro-inflammatory cytokine signaling that could contribute to enhanced asthma severity, as well as asthma exacerbations." (PMID 37638015, 2023). "Additionally, it will also be important to determine what factors are driving increased MYADM epithelial expression in asthma and the relative expression of MYADM on eosinophils in asthma." (PMID 34862427, 2021). "Little is known about the roles of MYADM in asthma and MYADM may likely have different and complex roles in the many cell types that express it." (PMID 34862427, 2021). "The clinical implications of this work suggest that in certain individuals with severe asthma, increased expression of MYADM and decreased expression of SP-A, may be a driving factor contributing to their more severe phenotypes." (PMID 34862427, 2021). "While there is much still to be discovered in regards to MYADM and asthma, we believe we are the first to acknowledge the potential importance of this previously unrecognized transmembrane protein in patients with asthma." (PMID 34862427, 2021). "A notable weakness of our study is that we were unable to associate MYADM expression on human eosinophils with asthma severity, as these samples were not available to us." (PMID 34862427, 2021). "Enhanced MYADM expression in histological sections from mice exposed to an allergic airways challenge was also observed and was in line with our previous finding of increased MYADM expression in lung epithelial cells from asthma patients compared with healthy controls." (PMID 37638015, 2023). "Finally, using a subset of participants in the Severe Asthma Research Program (SARP) cohort, we are the first to describe a significant association between epithelial expression of MYADM and parameters of airway inflammation, including peripheral blood eosinophilia." (PMID 34862427, 2021). "Specifically, increased MYADM expression significantly correlated with asthma and asthma severity in that healthy controls < non-severe asthma < severe asthma (p < 0.0001)." (PMID 34862427, 2021). "While we have opened to door to many new potentially relevant avenues of study for SP-A, MYADM and asthma, taken together, our studies bring to light a novel binding partner for SP-A that is necessary for SP-A to induce eosinophil apoptosis." (PMID 34862427, 2021). "To determine whether human eosinophils isolated from asthma patients would respond similarly, we isolated leukocytes from the peripheral blood and analyzed these cells by flow cytometry after incubation with SP-A, with or without pre-treatment with anti-MYADM." (PMID 34862427, 2021). "MYADM AEC mRNA expression significantly correlated with asthma severity, where healthy controls < non-severe asthma < severe asthma." (PMID 34862427, 2021).
eosinophilia (2 papers, 2021 to 2023). "Moreover, increased MYADM expression in airway epithelial cells also associated with increased peripheral blood eosinophilia and exhaled nitric oxide, as well as frequency of exacerbation." (PMID 37638015, 2023). "Moreover, MYADM expression in human airway epithelial cells was markedly increased in asthmatic patients compared with controls and its expression was positively associated with peripheral blood eosinophilia, exhaled nitric oxide, and the frequency of exacerbation." (PMID 37638015, 2023). "In the OVA mouse model of experimental allergen-induced inflammation and eosinophilia, disruption of the SP-A:MYADM interaction resulted in persistent eosinophilia and a delay in resolution, likely contributing to the increases in airway hyperreactivity measurements observed." (PMID 34862427, 2021). "While our functional studies with eosinophils show that blocking the SP-A:MYADM interaction resulted in more eosinophilia and worse lung function, the SARP III data suggested increased epithelial expression of MYADM is associated with increased eosinophilia and worse lung function." (PMID 34862427, 2021).
lung carcinoma (2 papers, 2022 to 2023). "The scrutiny of the two sources of information, datasets and published studies, reveals potential prognostic applications of MAL-family members as cancer biomarkers—for instance, MAL2 in breast cancer, MAL2 and MALL in pancreatic cancer, and MAL and MYADM in lung cancer—and other biomedical uses." (PMID 37345137, 2023). "Other stronger correlations were that of MAL (LUAD) and MYADM (LUSC) in lung cancer, which was the second most highly ranked in the 2020 ranking, with 12.5% of the new cancer cases, and that of MAL2 and MALL in PAAD, which was ranked twelfth, with 2.7% of the new cases." (PMID 37345137, 2023). "In our study, comparing MYADM with other known lung cancer biomarkers by bioinformatic methods, we found MYADM was associated with ICAM1 and RAC1, suggesting that MYADM may be a prognostic factor for NSCLC." (PMID 36061144, 2022). "In the future, MYADM may be a potential prognostic marker for lung cancer." (PMID 36061144, 2022).
prostate carcinoma (2 papers, 2022 to 2024). A carcinoma that arises from epithelial cells of the prostate gland. "A previous study showed that the expression of the main regulators of EMT, invasion, motility, and migration changed after MYADM knockdown, suggesting that overexpressed MYADM probably predicted subsequent lymph node metastasis in patients with prostate cancer." (PMID 39247591, 2024). "The MYADM gene was found to be associated with 5 years of biochemical recurrence in prostate cancer in most African American biomarkers studies lacking E26 transforming specific family fusion events." (PMID 36061144, 2022). "The ectopic expression of MYADM was confirmed in non-small-cell lung cancer (NSCLC), acute promyelocytic leukemia, prostate cancer, colon cancer, melanoma, and pancreatic ductal adenocarcinoma 15,17-21." (PMID 39247591, 2024).
pulmonary artery hypertension (2 papers, 2023 to 2024). "Previous studies identified a new regulatory model of the miR-182-3p/MYADM/KLF4/p21 axis in pulmonary hypertension vascular remodeling." (PMID 39247591, 2024).
coronary heart disease (1 paper, 2015). "For example, rs3184504, a nonsynonymous SNP in SH2B3 that was associated in GWAS with BP, coronary heart disease, hypothyroidism, rheumatoid arthritis, and type 1 diabetes, is a trans-eQTL for 6 of our 34 BP signature genes from the meta-analysis (FOS, MYADM, PP1R15A, TAGAP, S100A10, and FGBP2)." (PMID 25785607, 2015).
hepatocellular carcinoma (1 paper, 2022). A malignant tumor that arises from hepatocytes. "The expression of MYADM protein was up-regulated in metastatic melanoma and hepatocellular carcinoma tissues." (PMID 36061144, 2022).
lung adenocarcinoma (1 paper, 2024). A carcinoma that arises from the lung and is characterized by the presence of malignant glandular epithelial cells. "In addition, MYADM was positively associated with macrophages, neutrophils, and dendritic cells in both lung squamous cell carcinoma and lung adenocarcinoma (Cor > 0.3, P < 0.05), suggesting its role in regulating tumor immunity." (PMID 39247591, 2024).
lymph node metastasis (1 paper, 2024). "The clinical parameters in the TMA indicated a link between MYADM expression and lymph node metastasis." (PMID 39247591, 2024).
melanoma (1 paper, 2023). A malignant, usually aggressive tumor composed of atypical, neoplastic melanocytes. "Another example is the downmodulation of MYADM in melanoma cells, which are known to use two different modes of movement during migration in three-dimensional extracellular matrices." (PMID 37345137, 2023). "This implies that the downmodulation of MYADM in melanoma cells might favor ameboid over mesenchymal movement during invasion." (PMID 37345137, 2023).
myeloid leukemia (1 paper, 2022). A clonal proliferation of myeloid cells and their precursors in the bone marrow, peripheral blood, and spleen. "The expression level of MYADM mRNA is significantly increased during the differentiation of myeloid leukemia, and thus, can be used as a membrane marker for disease surveillance." (PMID 36061144, 2022).
respiratory infection (1 paper, 2023). "Interestingly, we found that respiratory syncytial virus (RSV), another common cause of respiratory infection in children, did not induce MYADM expression in epithelial cells suggesting viral specificity to MYADM upregulation." (PMID 37638015, 2023).
SAPHO syndrome (1 paper, 2019). SAPHO syndrome (acronym for Synovitis, Acne, Pustulosis, Hyperostosis and Osteitis) is an auto-inflammatory disease, mainly characterized by the association of neutrophilic cutaneous involvement and chronic osteomyelitis. "The down-regulation of MYADM may contribute to bone metabolism and delayed bone recovery in SAPHO syndrome." (PMID 31395074, 2019).
virus infection (1 paper, 2024). "Using mutagenesis based on the divergent ability of human parechovirus to engage with MYADM from several mammalian species, we identify specific amino acid residues within the fourth extracellular loop of MYADM as critical for virus infection." (PMID 38658526, 2024).
tumor (8 papers, 2021 to 2025). "MYADM expression was also downregulated in the tumour group, and the associated pathways were similarly diminished." (PMID 40429821, 2025). "The existing literature suggests that MYADM is a gene with dual functionality, promoting tumour growth while potentially acting as a suppressor under specific conditions." (PMID 40429821, 2025). "MYADM is involved in the progression of multiple cancers, including proliferation, differentiation, migration, invasion, and tumor immunity 15,17,18." (PMID 39247591, 2024). "This is especially evident in the cases of MALL, PLLP, and MYADM, whose function in normal and tumor cells needs further investigation using established cell model systems, and that in the case of MYADML2, which is yet to be examined." (PMID 37345137, 2023). "Moreover, we found that MYADM expression was significantly correlated with multiple clinicopathological parameters based on IHC staining, including tumor differentiation, TNM stage, T stage, lymphatic metastasis, and postoperative distant metastasis." (PMID 39247591, 2024). "Additionally, MYADM showed the largest difference in expression between these tumor tissues and the corresponding normal tissues in the Genotype-Tissue Expression (GTEx) database (Log2FC > 2, P < 0.01)." (PMID 39247591, 2024). "Further analysis showed that MYADM was nagetively associated with TMB, and was positively correlated with macrophages, neutrophils, and dendritic cells, suggesting its role in regulating tumor immunity." (PMID 36061144, 2022). "Moreover, MYADM was essential for tumor cell proliferation and migration." (PMID 36061144, 2022). "Upon analyzing the expression of 11 model genes in prostate PRAD, we observed significant differential expression of eight genes (MYADM, MPDZ, LTBP2, DENND4C, PROK1, DDIT4, IGFBP3, and CFD) between normal and tumor tissues." (PMID 38898043, 2024). "The results showed that MYADM was weak negatively correlated with TMB (p = 0.014, r = −0.08), but not with MSI (p = 0.256, r = 0.04), TMB has been found in a variety of tumor immunotherapy in recent years as an independent biomarker that can be used to predict the efficacy of immunotherapy." (PMID 36061144, 2022).